WAS (WASP actin nucleation promoting factor)
Diseases named in the same sentence as WAS in open-access papers (continued):
Sharing a sentence is not in itself a finding about the gene and the disease.
X-linked thrombocytopenia (16 papers, 2010 to 2024). "Clinical phenotypes caused by deletion or low expression of WASP due to pathogenic mutations in the WAS gene include typical WAS, X-linked thrombocytopenia (XLT), and X-linked neutropenia (XLN)." (PMID 38410787, 2024). "Approximately 89% of patients with the WAS gene mutations are classified as exhibiting a severe phenotype, 10% show a mild X-linked thrombocytopenia (XLT) phenotype, and a small number exhibit X-linked neutropenia." (PMID 33717090, 2021). "Flow cytometry-based assessment of intracellular WAS protein (WASP) is useful for screening patients suspected to have WAS or X-linked thrombocytopenia and neutropenia and for following up chimerism after hematopoietic stem cell transplantation or somatic reversion mosaicism." (PMID 34858394, 2021). "Binding of WASP and WIP is shown critical for normal platelet development, and mutations inhibiting this protein–protein interaction is associated with X-linked thrombocytopenia in WAS patients." (PMID 33717090, 2021). "The WASP-related pathologies include classical WAS (usually associated with defective WASP), X-linked thrombocytopenia (XLT, caused by residual point-mutated WASP), and X-linked neutropenia (XLN, caused by activating mutations)." (PMID 25709608, 2015). "Mutations in WASP gene can give rise to three different clinical phenotypes; classical WAS, X-linked thrombocytopenia (XLT) and X-linked severe congenital neutropenia (XLN)." (PMID 25200405, 2014). "Over 200 mutations in the WAS gene were found until today, where mutations leading to an absent or truncated WASP cause a more severe form of WAS while missense mutations with expression of mutant WASP are usually associated with the milder X-linked thrombocytopenia (XLT)." (PMID 36044170, 2023).
primary immunodeficiency (15 papers, 2015 to 2025). "At age six, molecular panel testing for genes associated with primary immunodeficiency identified a missense WAS gene variant." (PMID 37550789, 2023). "Wiskott–Aldrich syndrome (WAS) is a primary immunodeficiency caused by mutations in the gene encoding the hematopoietic-specific WAS protein (WASp)." (PMID 28512459, 2017). "The Wiskott–Aldrich syndrome (WAS) is a severe primary immunodeficiency caused by mutations in the Wiskott–Aldrich syndrome protein (WASp), a scaffold that promotes actin polymerization and links TCR stimulation to T cell activation." (PMID 26379669, 2015). "A primary immunodeficiency genetic panel identified a missense mutation in the WAS gene (c." (PMID 37550789, 2023). "Finally, we demonstrate differential circRNA expression in ADA-SCID and WAS, two primary immunodeficiencies which are caused by mutations in ADA or WAS, respectively." (PMID 28842720, 2017). "Here, we report the successful application of a CRISPR/Cas9-based gene editing platform to correct an extremely complex primary immunodeficiency, Wiskott–Aldrich Syndrome, through editing of the WAS locus in primary human HSPCs." (PMID 32788576, 2020). "Later, the same lab used the Gal4/UAS system to dissect the function of different human WAS mutant alleles by targeting their expression specifically to neutrophils and macrophages in WASp-null zebrafish (see poster: Primary immunodeficiencies)." (PMID 31519693, 2019). "Thus, genetic defects in WAS and WDR1 are clear examples of human syndromic primary immunodeficiencies with excessive inflammasome activation linked to dysregulation of the actin cytoskeleton, albeit with different pathogenetic mechanisms." (PMID 29146903, 2017).
lymphoma (13 papers, 2013 to 2026). A malignant (clonal) proliferation of B- lymphocytes or T- lymphocytes which involves the lymph nodes, bone marrow and/or extranodal sites. "Future studies of nuclear WASp may reveal whether dysregulation of β-catenin–TCF1 signaling is associated with increased frequency of lymphoma in WAS patients." (PMID 29078804, 2017). "WASP has been linked to Wiskott–Aldrich syndrome, a recessive disease in which the WASP-homology domain is often mutated causing WASP destabilization, dissociation from WAS/WASL-interacting protein family member 1 (WIP) and lymphoma predisposition." (PMID 33928032, 2021). "Since almost 90% of the malignancies in WAS patients are of lymphoreticular origin, we took the approach to study the killing response by WASp KO NK cells to lymphoma cells and hematopoietic grafts." (PMID 27477778, 2016).
autoimmune disease (11 papers, 2013 to 2026). A disorder resulting from loss of function or tissue destruction of an organ or multiple organs, arising from humoral or cellular immune responses of the individual to their own tissue constituents. "Humoral immunodeficiency caused by mutations in the WAS gene encoding WASp is associated with failure to respond to common pathogens and up to 40–70% of patients developing autoimmune disease with high titers of autoantibodies." (PMID 30894852, 2019). "To study the development of autoimmune disease in WAS KO mice, we employed an experimental model of antigen-induced arthritis." (PMID 24945741, 2014). "As an important role in the development of autoimmune disease has been identified for IL-17-producing T (Th17) cells, we analyzed Th17 cells and found a significant increase of Th17 cells in LNs of mBSA-treated knees of WAS KO mice." (PMID 24945741, 2014). "The absence or altered structures of WASp result in the Wiskott–Aldrich syndrome (WAS), a rare primary immunodeficiency disease, which is clinically characterized by thrombocytopenia, eczema, immunodeficiency, and increased risk of autoimmune diseases and lymphoid malignancies." (PMID 35116029, 2021).
neutropenia (11 papers, 2011 to 2025). A decrease in the number of neutrophils found in the blood. "Despite severe neutropenia, the fourth patient with a WAS mutation has presented a low rate of infections, receiving G-CSF only during infections." (PMID 39459363, 2024). "Very rare cases of neutropenia are associated with activating mutations in the gene encoding the WAS protein, resulting in an X-linked form of SCN." (PMID 39459363, 2024). "As WAS protein is involved in intracytoplasmic actin polymerization, mutations observed in patients with neutropenia lead to an increase in actin polymerization, accompanied by an increase in the podosome level and in apoptosis." (PMID 21595885, 2011). "Ten patients had “undetectable” RORγt, including those with CVID (P433), periodic fever (P238), STAT1 (P54), WAS (P154), chronic muco-cutaneous candidiasis (P379), two with neutropenia (P63 and P66), and three with SCID (P140, P394, and P365)." (PMID 32670274, 2020). "Broadly, these conditions can be divided into those where neutropenia is the predominating feature, such as in ELANE, GFI1, HAX1, CSF3R and WAS mutations and those where neutropenia is part of a multi-system disorder." (PMID 23758768, 2013). "Morphologic abnormalities due to abnormal differentiation in myeloid cells are also encountered in congenital, cyclic, dysgranulopoietic neutropenia cases with or without the WAS, GFI-1, and G6PC3 mutations, in myelodysplastic syndrome, and in a number of non-malignant disorders." (PMID 30040071, 2018). "Patients with GFI1 and WAS gain of function (GOF) mutations are very rare and seem to present with mild to moderate neutropenia, and there are no reports on alloHSCT in these patients." (PMID 31709206, 2019).
viral infection (9 papers, 2012 to 2024). "Despite a significant proportion of patients with WAS having recurrent viral infections, surprisingly little is known about the effects of WASP deficiency on antiviral immunity." (PMID 23141740, 2013). "Patients with WAS have recurrent viral infections, but relatively little is known about the mechanistic role of WASP in antiviral immunity." (PMID 23141740, 2013). "To investigate the ability of WAS KO mice to mount a protective immune response against viral infection and to investigate immunopathology, we challenged mice with LCMV (WE strain)." (PMID 23141740, 2013). "Overall, these findings indicate that there are intrinsic defects of cytotoxicity in WAS KO CD8+ T cells and that they play a significant role in the control of viral infection in vivo." (PMID 23141740, 2013). "Furthermore, WAS KO mice showed persistence of viral replication and a hepatic T-cell infiltrate 15 days after infection, whereas by that time, wild-type C57BL/6 animals had cleared viral infection and showed no sign of T-cell infiltration." (PMID 23141740, 2013).
actinopathies (8 papers, 2021 to 2025). "HSCT is a known treatment for other hematopoietic actinopathies such as WAS and DOCK8 deficiency and would likely rescue HEM1 in all relevant hematopoietic cell lineages." (PMID 35869404, 2022). "Rescue of T-cell activation by the addition of exogenous IL-2 in actinopathies was previously reported by our group and others in CARMIL2 deficiency and WAS protein knockout mouse model." (PMID 40748410, 2025). "A literature review of actine-related IEIs showed that only diseases affecting the CDC42 GTPase pathway, namely WAS and DOCK8, have been reported in large enough numbers to allow a comparative analysis of different actinopathies." (PMID 40860338, 2025). "Although we did not observe a clear genotype-phenotype correlation between patients with different types of actinopathies, specific genetic defects mainly from the CDC42 GTPase pathway including WAS and DOCK8 showed higher mortality in the context of severe genetic mutations." (PMID 40860338, 2025).
leukemia (8 papers, 2016 to 2025). A malignant (clonal) hematologic disorder, involving hematopoietic stem cells and characterized by the presence of primitive or atypical myeloid or lymphoid cells in the bone marrow and the blood. "While WAS/WIP behaves as tumor suppressor genes, N-WASP accelerated leukemia progression." (PMID 33717090, 2021).
colitis (7 papers, 2016 to 2022). Inflammation of the colon. "WAS-deficient patients can present with phenotype similar to IL-10R deficient patients including recurrent infections, colitis and perianal disease." (PMID 29725003, 2018).
congenital neutropenia (7 papers, 2011 to 2024). "A genetic linkage study of a pedigree with suspected sex-linked genetic transmission revealed mutations in the WAS gene (encoding Wiskott-Aldrich syndrome protein) in a family with severe congenital neutropenia, and more recently in four other families." (PMID 21595885, 2011). "This phenotypic difference, despite the shared involvement of the WAS gene, is due to functional differences in the respective mutations (WAS protein activation in congenital neutropenia and defective WAS protein activity in the classical syndrome)." (PMID 21595885, 2011). "This group includes congenital neutropenia caused by mutations in ELANE, GFI1, HAX1, WAS (X-linked neutropenia), CSF3R, and SRP54 genes." (PMID 31709206, 2019). "None of the genes mutated in congenital neutropenia, with exception of WAS, have been linked with bone cell function or bone phenotypes." (PMID 29879182, 2018).
lupus (6 papers, 2015 to 2022). "Studies using B cell specific deficiency of Wiskott-Aldrich syndrome protein (WAS) as a lupus mice model also shows significantly elevated ANA levels and glomerulonephritis." (PMID 26068236, 2015). "Surprisingly, in the current study, we also show that the WAS chimera model is not impacted by global Il12rb2 deficiency and our previous work has shown that B cell-intrinsic IFNAR is also dispensable for lupus development in this model." (PMID 30740104, 2019).
atherosclerosis (3 papers, 2022 to 2025). A disease characterized by the build-up of fatty material and calcium deposition in the arterial wall resulting in partial or complete occlusion of the arterial lumen. "We identified 12 lactylation-related genes that are more reliably associated with atherosclerosis: five upregulated genes (LSP1, IKZF1, MNDA, RCC2, and WAS) and seven downregulated genes (CSRP2, PPP1CB, CSRP1, HEXIM1, CALD1, PDLIM1, and RANBP2)." (PMID 40248193, 2025).
colorectal cancer (3 papers, 2016 to 2022). A primary or metastatic malignant neoplasm that affects the colon or rectum. "The concurrent presence of the mutated forms of APC and WAS was not specific to HB, it has been reported that dysregulation of WAS or APC relates to the onset and progression of other cancers, like decreasing WAS expression in chronic myeloid leukemia and APC mutant in colorectal cancer." (PMID 30619485, 2018).
lung carcinoma (3 papers, 2011 to 2022). "Moreover, SASH3 is associated with gene regulatory sites (such as WAS and CD53) in lung cancer, which has diagnostic value for lung cancer metastasis." (PMID 36408131, 2022). "For example, VAMP2, the top most level-1 gene in the Lung Cancer data set, has a GMI value of 7.19, showing discriminating power which appears even stronger than WAS, the top most level-1 gene in the SRBCT data set." (PMID 21909426, 2011).
cervical cancer (2 papers, 2021 to 2025). A primary or metastatic malignant neoplasm involving the cervix. "The associations between the expression of WAS expression and clinical characteristic of patients with cervical cancer in TCGA-CESC." (PMID 34222242, 2021).
Congenital thrombocytopenia (2 papers, 2023 to 2024). Thrombocytopenia with congenital onset. "Male patients with congenital thrombocytopenia and small platelets must have their WAS gene mutation and WASP expression evaluated as soon as possible using molecular genetic techniques and protein detection." (PMID 38410787, 2024).
dermatitis (2 papers, 2018 to 2022). An inflammatory process affecting the skin. "Our observations point to IL-17A, but not IL-4, contributing to the development and/or maintenance of the skin inflammation described in WAS−/− animals." (PMID 35265075, 2022). "Four week old WT and WAS−/− mice were co-housed for two weeks and then assessed for ear skin inflammation." (PMID 35265075, 2022). "Loss of T and B cells abolished WAS-associated skin inflammation, as determined by normalizing for the non-T cell CD45+ cell (CD45+CD4−CD8β−γδ−) compartment between WAS−/− and WAS−/−Rag2−/−." (PMID 35265075, 2022). "Therefore, we assessed the role of IL-4 and IL-17 in the development of skin inflammation using WAS−/−IL-4-/- and WAS−/−IL-17−/− mice." (PMID 35265075, 2022). "Preliminary studies co-housing WT mice in the same microbial environment as the WAS−/− BALB/c mice was not sufficient to induce skin inflammation." (PMID 35265075, 2022). "Moreover, cutaneous inflammation was only observed in the full absence of WASp, WAS+/− mice showing no overt skin inflammation." (PMID 35265075, 2022).
DiGeorge syndrome (2 papers, 2019 to 2022). "Genetic diagnosis was done for 24 patients with CID with syndromic defects: WAS gene variants were detected in 6 patients from 5 different families; 4 patients with DiGeorge syndrome were confirmed by FISH." (PMID 35482138, 2022).
osteosarcoma (2 papers, 2023 to 2026). A usually aggressive malignant bone-forming mesenchymal neoplasm, predominantly affecting adolescents and young adults. "As a potential intervention target for immunotherapy, the relationship between WAS genes and osteosarcoma has not yet been revealed." (PMID 37031292, 2023).
periodontitis (2 papers, 2025 to 2026). An acute or chronic inflammatory process that affects the tissues that surround and support the teeth. "We identified HCK, NCKAP1L, and WAS as key diagnostic biomarkers for periodontitis-related unstable plaques and developed a diagnostic nomogram to facilitate clinical risk assessment." (PMID 40136451, 2025). "Following the criteria of an AUC > 0.7 and significant expression differences in datasets GSE613451 and GSE41571, we ultimately identified HCK, NCKAP1L, and WAS as biomarkers for unstable atherosclerotic plaques associated with periodontitis." (PMID 40136451, 2025). "By screening the node genes of the PPI network and applying various machine learning methods, we identified HCK, NCKAP1L, and WAS as biomarkers of periodontitis-related unstable plaques." (PMID 40136451, 2025). "In terms of the shared molecular mechanisms underlying periodontitis and renal cell carcinoma, six genes (IKZF1, LGALS1, LSP1, MNDA, VIM and WAS) were consistently upregulated in both disease tissues, indicating their potential involvement in the common pathogenesis of the two diseases." (PMID 42157182, 2026).
Turner syndrome (2 papers, 2017 to 2023). Turner syndrome is a chromosomal disorder associated with the complete or partial absence of an X chromosome. "Eight TFs and four ERFs are among the differentially expressed genes, as well as eight genes associated with Turner syndrome (PROCR, NR3C1, INSR, APOB, BMP15, F8, IL6, and WAS) and two genes that are haploinsufficient in humans (RAD50 and SLC33A1)." (PMID 28818098, 2017).
acne (1 paper, 2017). An inflammatory process of the sebaceous glands which is characterized by comedones, nodules, papules and/or pustules on the skin. "Interestingly, PAPA syndrome (pyogenic sterile arthritis, pyoderma gangrenosum and acne) caused by mutations in the cytoskeletal adapter PSTPIP1 (which binds to WASp) shares cytoskeletal features with WAS and is also associated with overt IL-1β production." (PMID 29146903, 2017).
Arthritis (1 paper, 2014). Inflammation of a joint. "Adoptive transfer of WT Breg cells ameliorated arthritis in WAS KO recipients and restored a normal balance of Treg and Th17 cells." (PMID 24945741, 2014). "We observed that WAS KO mice developed exacerbated arthritis, which correlated with a decrease in Breg and Treg cells and increase in Th17 cells in draining LNs and spleen." (PMID 24945741, 2014). "WAS KO mice developed exacerbated arthritis as shown by the accumulation of mononuclear cells in the knee joint compared with those in C57BL/6 animals." (PMID 24945741, 2014).
Chediak-Higashi syndrome (1 paper, 2019). ChC)diak-Higashi syndrome (CHS) is a rare severe genetic disorder generally characterized by partial oculocutaneous albinism (OCA), severe immunodeficiency, mild bleeding, neurological dysfunction and lymphoproliferative disorder. "Data obtained in mice knockout for the Wiskott-Aldrich syndrome (WAS) protein or in cytotoxic T lymphocyte (CTL) clones derived from Chediak-Higashi syndrome (CHS) patients gave some cues to demonstrate the physiological relevance of this mechanism." (PMID 30759880, 2019).
colon cancer (1 paper, 2020). "Our results support a hypothesis that transgelin interacts with PARP1 and regulates the expression of downstream key genes (CALM1, MYO1F, NCKIPSD, PLK4, RAC1, WAS and WIPF1), which are mainly involved in the Rho signaling pathway in the human RKO colon cancer cells." (PMID 32774160, 2020).
diabetes (1 paper, 2013). "In chimeric or transgenic RIP-GP/WAS KO mice, we observed T-cell infiltration around the islets of Langerhans, which is typically associated with the onset of diabetes." (PMID 23141740, 2013).
head and neck cancer (1 paper, 2024). A primary or metastatic malignant neoplasm affecting the head and neck. "We identified one protein for each of bladder [WAS, 0.54 (0.39–0.73)], brain [GFAP, 1.55 (1.31–1.86)], and head and neck cancers [TPP1, 1.33 (1.16–1.52)]." (PMID 38750076, 2024).
hyperlipidemia (1 paper, 2025). "In this study, HCK, LYN, WAS, and PTK2B were identified as hub genes using Maximal Clique Centrality, holding significant implications for future research on hyperlipidemia." (PMID 41446394, 2025).